TLR4 (toll like receptor 4)
Diseases named in the same sentence as TLR4 in open-access papers (continued):
Sharing a sentence is not in itself a finding about the gene and the disease.
glaucoma (continued). "Modulators of TLR4 signaling have already been developed, and the studies described here suggest that such modulators could be used to target OS in glaucoma." (PMID 28053689, 2016). "Taken together, our results indicate that peripheral (non-eye related) bacterial activity and/or products are potential contributing factors to glaucoma pathophysiology through upregulation of the TLR4 and the complement system pathways and microglial activation in the affected tissues." (PMID 25180891, 2014). "However, the relationship between gut microbiome alterations, their pro-inflammatory effects, and TLR4 variations in glaucoma remains unclear." (PMID 39726974, 2024). "In addition, neuroinflammatory responses involving astrocytes and microglia are recognized in the ONH in glaucoma, and evidence from both human glaucoma patients and animal models of glaucoma suggest that immune responses are mediated, at least in part, by TLR4." (PMID 35619185, 2022). "Interestingly, combined analysis showed rs1927911, rs12377632, and rs2149356 in the allele contrast model were strongly associated with glaucoma (POAG and NTG) suggesting that the POAG and NTG share some pathogenesis factors that may relate to TLR4." (PMID 30877182, 2019). "In the present study, we used an ex vivo rat glaucoma model to investigate the microglial signaling pathway mediating RGC death and describe key roles of TLR4 and IL-1β." (PMID 40722741, 2025). "By downregulating Toll-like receptor 4 (TLR4) and activating the Akt/PTEN signaling pathway, Cav-1 reduces RGC apoptosis, underscoring its potential as a novel therapeutic target for glaucoma." (PMID 40243482, 2025). "Here, we investigate the role of an endogenous Toll-like receptor 4 (TLR4) ligand, FN-EDA, in the development of glaucoma utilizing a transgenic mouse strain (B6.EDA+/+) that constitutively expresses only FN containing the EDA isoform." (PMID 35619185, 2022). "On the other hand, expression of miR-204 in glaucoma and optic nerve injury is high, which by disrupting GAP-43 disrupts the MyD88/TLR4/NFKB pathway and ultimately kills retinal cells (N.)." (PMID 34646884, 2021). "When stratified by the subtype of glaucoma, our results demonstrated that TLR4 polymorphisms may have a tendency to influence the phenotypic features in POAG patients, instead of NTG patients, indicating that the pathogenesis and effect of TLR4 may be different between POAG and NTG." (PMID 31428642, 2019). "However, the TLR4 polymorphisms have not been completely elucidated in both types of glaucoma." (PMID 30877182, 2019). "Therefore, the TLR4 may play a role in glaucoma pathogenesis." (PMID 30877182, 2019). "Expressions of TLR4 and angiotensin II type 1 receptor (AGTR1) are increased in a mouse model of glaucoma, and an AGTR1 antagonist suppresses neurodegeneration in the mouse retina by inhibiting the TLR4-apoptosis signal-regulating kinase 1 pathway." (PMID 28053689, 2016). "Our findings provide preliminary evidence for the RGC protective and microglia-associated neuroinflammatory reduction effects of ADSC-EVs by inhibiting the TLR4/MAPK/NF-κB proinflammatory cascade response in OHT mice, indicating the therapeutic potential ADSC-EVs or adjunctive therapy for glaucoma." (PMID 38504301, 2024). "Along with TLR4 expression differentiation, DAMPs such as tenascin-C and FN+EDA have also been identified as differentially expressed in the ONH and retina in glaucoma." (PMID 37686046, 2023). "TLR4 pathway related genes, downstream ECM genes, and DAMPs such as tenascin-C and heat shock proteins have been identified as differentially expressed in the human ONH and retina in glaucoma." (PMID 36911656, 2022). "The TLR4 pathway is a fibroinflammatory pathway that can modulate the function of the TM, specifically by altering the TM’s rate of deposition of ECM, leading to the impairment of aqueous humor outflow and the progression of glaucoma." (PMID 35912101, 2022).
glaucoma (continued). "Nowadays, it is still not completely clear how TLR4 SNPs are associated with OAG, but a series of experimental evidence has addressed the role of TLR4 signaling in the pathophysiology of glaucoma." (PMID 31428642, 2019). "Reduced expression of genes involved in the pathogenesis of glaucoma was also observed, including chemokines and cytokines (GFAP, Caspase-8, TNFα, IL-1β, IL-6, IL-18, MIP-1α, MIP-1β, MIP-2, MCPI, and IP10), components of the complement cascade (C3, C1Q), Toll-like receptor pathway (TLR4)." (PMID 38562304, 2024). "It is known that increased TGFβ2 levels in glaucoma may be due to epigenetics, suggesting that it is the increased TGFβ signaling that occurs first leading to production of excess ECM and DAMPs, which would then activate TLR4 leading to a feedforward signaling loop." (PMID 35912101, 2022).
nonalcoholic steatohepatitis (43 papers, 2010 to 2025). "For example, Chlorogenic acid and EGCG alleviate liver inflammation by directly inhibiting TLR4, thereby slowing the progression of nonalcoholic steatohepatitis (NASH) and liver injury caused by Pseudomonas aeruginosa infection." (PMID 41154556, 2025). "The overexpression of TLR4 is associated with the accumulation of fat granules in the liver and lipid degeneration of liver cells, which has been verified in non-alcoholic steatohepatitis of mice or rats." (PMID 38275739, 2024). "As reported, GQD alleviates nonalcoholic steatohepatitis associated liver injuries via anti-inflammatory response and inhibition of toll-like receptor 4 signaling pathways." (PMID 33643422, 2021). "Regarding TNFα signaling via NF-κB in endothelial cells, in animal studies, Pecam1 KO mouse developed nonalcoholic steatohepatitis, whereas Tlr4 KO mouse and Il15 KO mouse were protected from NAFLD." (PMID 37491046, 2023). "Resolvin D1 mitigates non-alcoholic steatohepatitis by suppressing the TLR4-MyD88-mediated NF-kappa B and MAPK pathways and activates the Nrf2 pathway in mice." (PMID 34179049, 2021). "CLD, such as nonalcoholic steatohepatitis (NASH), is highly associated with the triggering of TLR4 signaling by gut-derived bacteria and cell death products." (PMID 34205789, 2021). "The purpose of this study was to investigate the effects of Qutan Huoxue Formula (QHF) on liver injury in mice with nonalcoholic steatohepatitis (NASH) by upregulating SOCS1 to inhibit the TLR4/NF-κB signaling pathway." (PMID 33293985, 2020). "Recent studies have demonstrated the mechanism of leptin-mediated upregulation of CD14 and TLR4 in nonalcoholic steatohepatitis." (PMID 26484872, 2015). "Subsequent barrier dysfunction exposes the liver to dual insults: endotoxin assault and persistent gut-derived pathogen-associated molecular patterns, mechanistically explaining the characteristic TLR4/MyD88 pathway hyperactivation in non-alcoholic steatohepatitis (NASH) patients." (PMID 40980312, 2025). "Moreover, in a data set downloaded from the GEO database (accession code GSE63067), gene expression of Tlr4, Nox2, Rac1 and Rac2 was remarkably increased in patients with non-alcoholic steatohepatitis compared with heathy controls." (PMID 29269727, 2017). "TLR4 signaling plays pivotal roles in the pathogenesis of non-alcoholic steatohepatitis." (PMID 26474417, 2015). "Experimental studies in models of non-alcoholic steatohepatitis (NASH) and neurodegenerative diseases have demonstrated that caffeine downregulates toll-like receptor 4 (TLR4)-mediated signaling, a key initiator of innate immune responses." (PMID 40507194, 2025). "The activation of TLR signaling plays a key role in hepatic inflammation and fibrosis, with TLR4 and TLR2 having essential roles in the progression of non-alcoholic steatohepatitis." (PMID 39599705, 2024). "The activation of Toll-like receptor (TLR) signaling is key in the process of liver inflammation and fibrosis, with TLR4 and TLR2 serving crucial roles in the progression of non-alcoholic steatohepatitis." (PMID 39599705, 2024). "SLBZS treatment inhibited the TLR4/p38 MAPK signaling pathway, attenuating lipid metabolic disturbance, reducing IL-1β, TNF-α, and IL-6 levels, and reversing non-alcoholic steatohepatitis progression." (PMID 32460745, 2020). "In nonalcoholic steatohepatitis, leptin can upregulate CD14 expression through JAK-STAT3 signaling pathway and it has been demonstrated that CD14 can activate CD14-dependent TLR4 pathway to induce an inflammatory response." (PMID 28250578, 2017). "Several studies have shown that TLR4 signaling is involved in the pathogenesis of various liver diseases, such as alcoholic liver disease (ALD), non-alcoholic steatohepatitis (NASH) and chronic hepatitis C." (PMID 26636761, 2015).
nonalcoholic steatohepatitis (continued). "Similarly, in non-alcoholic steatohepatitis (NASH), Kupffer cell activation via TLR4 and NLRP3 inflammasomes promotes release of cytokines such as IL-1β and IL-18." (PMID 41585231, 2025). "Fatty acid deposition in the liver can activate a number of pro-inflammatory signaling pathways such as the Toll-like receptor 4 (TLR4) pathway, which may be important in the pathogenesis of nonalcoholic steatohepatitis." (PMID 25906757, 2015). "In an animal model of non-alcoholic steatohepatitis (NASH), various factors such as metabolic disorders, oxidative stress, and translocated bacterial products activated Kupffer cells via TLRs, especially TLR4, leading to increased NF-κB signaling and pro-inflammatory cytokine production." (PMID 40185720, 2025).
cerebral infarction (42 papers, 2009 to 2026). An ischemic condition of the brain, producing a persistent focal neurological deficit in the area of distribution of the cerebral arteries. "Toll-like receptor 4 (TLR4) on the surface of microglia plays an important role in regulating the inflammatory response caused by cerebral infarction, cerebral hemorrhage and TBI." (PMID 36204225, 2022). "TLR4 was upregulated after ischemia-induced stroke, and mice deficient in TLR4 exhibited less-severe cerebral infarction and neurological deficit compared with wild-type counterparts." (PMID 33057840, 2021). "After cerebral infarction, it has been confirmed that the infective injury around ischemic tissue becomes the direct cause of cerebral edema but does infective injury after cerebral infarction correlate to TLR4 and TLR2 levels?" (PMID 20182634, 2009). "As reported, the intra‐peritoneal injection of TAK‐242 (an antagonist for TLR4) markedly reduced cerebral infarction and improved neurologic function in mice with acute cerebral ischemia/reperfusion injury." (PMID 39822731, 2025). "According to these findings, we suggest that TM treatments ameliorate cerebral infarction possibly by downregulating JNK/TLR4/T3JAM-mediated signaling in activated microglia." (PMID 39391701, 2024). "At the same time, it was shown that aspirin-triggered lipoxin reduced cerebral infarction through the regulation of TLR4/NF-κB-mediated endoplasmic reticulum stress in a mouse model." (PMID 37033937, 2023). "Sal B improved neurological dysfunction, reduced the size of cerebral infarcts and cerebral edema, and inhibited the inflammatory response following cerebral I/R injury by downregulating TLR4, p‐p38MAPK, p‐JNK, nuclear NF‐κB, and IL‐1β production." (PMID 37904689, 2023). "The inhibition of TLR4-NOX4 signalling significantly reduces the infarct volume after cerebral infarction and reperfusion and improves neurological functional scores, demonstrating that TLR4 represents a possible therapeutic target for CCI." (PMID 36952071, 2023). "It has been reported that while activation of TLR4 exacerbates cerebral infarction, inhibition of the receptor suppresses pro-inflammatory responses and attenuates brain injury." (PMID 36117859, 2022). "Previous studies have shown that aspirin reduced cerebral infarction by modulating the TLR4/NF-κB-mediated endoplasmic reticulum stress in the mice model." (PMID 35966335, 2022). "The depletion of circTTC3 can decrease cerebral infarction, brain edema, and apoptosis, and attenuates cerebral infarction via the miR-372-3p/TLR4 axis." (PMID 36330428, 2022). "This study demonstrated that TLR4/NF-κB pathway was highly activated in the cerebral infarction rats." (PMID 35966335, 2022). "The TLR4/NF-κB signaling pathway and the inflammatory response were activated in the cerebral infarction animal model." (PMID 35966335, 2022). "The results indicated that the expression levels of TLR4, p65, p-p65, and p-IκB in cerebral infarction rats were significantly increased compared with the control group, which were remarkably attenuated in the MCAO + sh-HMGA2 group." (PMID 35966335, 2022). "In conclusion, we identified that circTTC3 regulated CIR injury and NSCs by the miR-372-3p/TLR4 axis in cerebral infarction." (PMID 33579365, 2021). "In this study, we found that circTTC3 was able to promote CIR injury and inhibit NSC proliferation and differentiation by the miR-372-3p/TLR4 axis in cerebral infarction." (PMID 33579365, 2021). "In summary, our study determined that DPSCs‐Exos contributed to the inhibition of HMGB1/TLR4/MyD88/NF‐κB pathway and alleviated the cerebral I/R damage (including brain oedema, cerebral infarction and neurological deficit) in mice after tMCAO." (PMID 34231932, 2021). "We identified a novel role of circTTC3 in regulating CIR injury and NSCs by the miR-372-3p/TLR4 axis in cerebral infarction." (PMID 33579365, 2021).
cerebral infarction (continued). "This study investigated the relationship between anti-inflammatory responses of paeonol and signaling pathways of TLR2 and TLR4 in cerebral infarct." (PMID 28101118, 2016). "A prior study showed that compared with vehicle control, TAK-242 significantly reduced cerebral infarction, improved neurologic function, and inhibited the phosphorylation of downstream protein kinases in TLR4 signaling pathway." (PMID 26830013, 2016). "Manipulating the expression of these necroptosis-related genes, such as TLR4, using miRNAs or lncRNA could potentially aid in reducing ischemia–reperfusion injury or the extent of cerebral infarction." (PMID 39743646, 2025). "However, the results can be inhibited by TLR4 antagonist, which decreases the volume of cerebral infarction, protects BBB integrity, and improves neurological function in I/R mice." (PMID 40289983, 2025). "In summary, ALO may reduce HI insult‐induced apoptosis and cerebral infarction by inhibiting glial cell activation and neuroinflammation mediated by the TLR4/MyD88/NF‐κB signaling pathway, thereby improving long‐term neurological function." (PMID 38888378, 2024). "Consequently, it diminishes cerebral infarction size, lowers cerebral water content, improves neurological deficits, reduces the TLR4 inflammatory factor expression and inhibits cell apoptosis." (PMID 38769994, 2024). "The experimental part of this study also showed that XNJ significantly improved the neural function of tMCAO mice, reduced the area of cerebral infarction, reduced inflammation-related factors such as TLR4, MyD88, NF-kappa B in ischemic site, and significantly reduced BBB permeability." (PMID 35646156, 2022). "Therefore, the TLR4/NF-κB signaling pathway is closely related to cerebral infarction-induced brain injury." (PMID 35966335, 2022). "Moreover, downregulation of HMGA2 had a protective effect on the brain damage derived from cerebral infarction by mediating the TLR4/NF-κB pathway." (PMID 35966335, 2022). "Thus, we conclude that circTTC3 regulates CIR injury and NSCs by the miR-372-3p/TLR4 axis in cerebral infarction." (PMID 33579365, 2021). "Moreover, ASA treatment improved the inflammatory response in cerebral infarction in mice thanks to downregulation of both TLR4 (toll-like receptor 4) and NF-κB expression, which led to endoplasmic reticulum (ER) stress inhibition." (PMID 34073241, 2021). "Thus, YZR extract treatments reduce cerebral infarction partially through the downregulation of JNK-mediated TLR4/T3JAM- and ASK1-related inflammatory signaling at 1 day after reperfusion." (PMID 34419138, 2021). "Moreover, YZR extract treatments exert neuroprotective effects against cerebral infarction partially through the downregulation of TLR4-mediated inflammatory signaling in the acute phase of transient MCAo." (PMID 34419138, 2021). "TLR2 and TLR4 knockout reduces inflammation, decreases the cerebral infarction area, and improves the neurological function score in MCAO mice; therefore, targeting the TLR signal may become an important treatment strategy for cerebral ischemic injury." (PMID 25928750, 2015). "Previous studies have reported that TLR4-mediated signaling causes JNK, p38 MAPK, and NF-κB activation, which induces the production of pro-inflammatory factors, including iNOS, COX-2, TNF-α, and IL-6, in the ischemic area, further exaggerating BBB disruption and cerebral infarction." (PMID 34419138, 2021). "Also, purified anthocyanin extracts (PAEs) could decrease the cerebral infarction volume and brain damage through Toll-like receptor 4 (TLR4) /NF-κB and NLRP3 pathways." (PMID 32581721, 2020). "The protection of ischemic postconditioning on ischemia/reperfusion-induced cerebral infarction, cerebral edema and neurological dysfunction is associated with its attenuation of apoptosis, and inhibition of neuroinflammation via modulation of the TLR2 and TLR4 pathways." (PMID 24460643, 2014).
cerebral infarction (continued). "Overall, the findings imply that TM treatments protect against cerebral infarction at least partly by suppressing the interaction between JNK and TLR4 in microglia in the cortical ischemic rim 2 days after transient MCA occlusion." (PMID 39391701, 2024). "We calculated the water content of brain tissue and the infarction size (as determined by TTC stain) to evaluate the influence of OMT on the expression of TLR4, TLR2, MyD88 and NF-κB in focal cerebral infarction in rats." (PMID 20182634, 2009). "By reducing the entry of LPS into the blood and inhibiting the activation of TLR-4 in the brain, PLP-3 can alleviate inflammatory levels in brain tissue and the whole body, ultimately improving the recovery of cerebral infarction and neurological function in MCAO mice." (PMID 39675265, 2025). "In this study, propofol pretreatment significantly attenuated brain infarction in the WT mice, but not in the TLR4 KO mice, indicating the involvement of the TLR4 pathway in the neuroprotective effects of propofol." (PMID 36117859, 2022).